TRAJ12 (T cell receptor alpha joining 12)
Gene: T-cell receptor joining (J) gene on chromosome 14 (22,531,939 to 22,531,998, forward strand). Ensembl gene ENSG00000211877.
Diseases named in the same sentence as TRAJ12 in open-access papers:
TRAJ12 is named in the same sentence as 1 disease in open-access papers, as found by Europe PMC text mining. Sharing a sentence is not in itself a finding about the gene and the disease. The quoted sentences say what the papers report.
cancer (2 papers, 2020 to 2025). A tumor composed of atypical neoplastic, often pleomorphic cells that invade other tissues. "Of the remaining cancer-activated MR1-restricted TCRs, some used the MAIT cell–preferred TRAJ20 and TRAJ12 to generate a similarly placed tyrosine and others used TRAJ26, TRAJ47, or TRAJ32 to encode this tyrosine residue." (PMID 39744940, 2025). "Within all the three tissue compartments examined for each of the three cancer types, TRAJ33 was the most commonly used Jα segment whereas TRAJ12 and TRAJ20 were detectable only in a minority of MAIT cells." (PMID 32849590, 2020).